HLA-B (major histocompatibility complex, class I, B)
Diseases named in the same sentence as HLA-B in open-access papers (continued):
Sharing a sentence is not in itself a finding about the gene and the disease.
tumor (continued). "It has been reported that the absence of HLA‐I (e.g. HLA‐A, HLA‐B, HLA‐C) expression is a common finding in different tumor tissues and is a major mechanism used by tumor cells to escape T cell‐mediated immune surveillance." (PMID 35229456, 2022). "In tumours with microsatellite instability (MSI), which are highly mutated and generally respond well to ICB, mutations in HLA-B were enriched compared to non-MSI tumours, possibly rendering these tumours resistant to ICB." (PMID 36476325, 2022). "The importance of antigen presentation in immune-oasis SCLC is further supported by MHCII-related molecules, such as HLA-B, TAP1, and CD74, which are all extensively overexpressed in this tumor phenotype and strongly interconnected according to string maps and network analysis." (PMID 34200100, 2021). "Finally, we also noted a positive correlation between HLA-B HED and enrichment of immune-related gene expression in tumor samples." (PMID 34732240, 2021). "CYT levels were significantly associated with tumor immune response factors, such as CD19, CD86, LTA, HLA-B, LAG3 and A2AR, in primary tumors but not in metastatic sites (lower row)." (PMID 33476333, 2021). "Furthermore, ligands Galectin-3 and HLA class II were increased in monosomy 3 tumours and the expression of LAG3 correlated with the presence of an inflammatory phenotype (T cell fraction, macrophages, HLA-A and HLA-B expression: all p < 0.001)." (PMID 34503258, 2021). "HLA-B and its ligand LILRB2 were found to be downregulated in LUAD tumor cells." (PMID 32549766, 2020). "Additionally, miR-9, which functions as a tumor suppressor in NPC55, positively regulated the expression of MHC class I genes (such as HLA-B and HLA-F) in NPC12." (PMID 32308549, 2020). "Tumor regions analyzed were either predicted to have all loci (HLA-A, HLA-B, and HLA-C) subject to LOH, or no loci affected." (PMID 29107330, 2017). "Tumor tissue of 197 patients with resected pulmonary adenocarcinoma was analyzed for the presence of CD8+ T cells and the expression of β2-microglobulin, HLA-A, HLA-B/C and HLA-E." (PMID 26658106, 2016). "We consistently found that treating NB4 cells with butyrate causes a significant downregulation of the mRNA levels of HLA-A and HLA-B. Truly, the cellular context may determine whether STAT1 acts as tumor promoter or as a tumor suppressor." (PMID 24810717, 2014). "Thirteen tumours presented total HLA-ABC loss, five selective losses of HLA-A antigens and one absence of HLA-B antigens." (PMID 8956796, 1996). "We found 13 tumours presenting total HLA-ABC loss, five with selective loss of HLA-A antigens and one with absence of HLA-B antigens." (PMID 2257212, 1990). "HLA-A and HLA-B belong to MHC class I antigens, and former research have shown that abnormal MHC-I expression and function regulation may be hijacked by tumor cells to evade immune surveillance, thereby promoting tumor progression and impairing the efficacy of cancer immunotherapy." (PMID 41001029, 2025). "In contrast, the downregulation of HLA-DRA, HLA-A, HLA-B, and HLA-C, which are components of the MHC antigen presentation machinery, suggests a disruption in antigen presentation pathways, further hindering the immune system’s ability to recognize and eliminate tumor cells." (PMID 39860532, 2025). "Furthermore, antigen-presenting molecules and immune molecular interactions, such as those between HLA-A, HLA-B, HLA-C, HLA-E, and HLA-F with CD8A and CD8B, appeared to be significantly up-regulated in tumor tissues, while their presence in normal tissues was comparatively diminished." (PMID 40723292, 2025). "Given the potential relevance of this response regarding tumor immunogenicity, and eventually for leveraging the efficacy of ICI-based therapies, we validated the effect of CM272 on the expression of chemokine CCL5 and different MHC genes such as HLA-A, HLA-B and HLA-C." (PMID 39810240, 2025).
tumor (continued). "Tumours with a low MITF expression showed an increase in the numbers of CD3D (p = 0.048), CD8A (probe 3: p = 0.01), and CD68 (two probes, p = 0.001 and p = 0.004) cells, as well as a higher expression of HLA-A (three probes: p = 0.003, p < 0.001, and p = 0.002) and HLA-B (p = 0.004)." (PMID 37240204, 2023). "Interestingly, this population of cells may also be involved in tumor antigen presentation, since genes for MHC-I molecules (HLA-A, HLA-B, HLA-C, HLA-E, and HLA-F) were highly expressed in this cluster." (PMID 37533434, 2023). "HLA-B and HLA-C also showed the sametrend but lacked statistical power due to the low number of peptides.The fold changes between tumor and paired normal samples are alsohighly consistent on RNA and protein levels, confirming that the overexpression waslargely driven at a transcriptional level." (PMID 37857377, 2023). "Moreover, the majority of PDS showed strong MHC-I expression and upregulated HLA class I molecules (HLA-A, HLA-B, HLA-C and HLA-E, corresponding in humans to the MHC class I) that are involved in tumor neoantigen presentation to tumor-specific CD8+ T lymphocytes leading to tumor cell apoptosis." (PMID 36465341, 2022). "In addition, Kaplan Meier survival analysis showed that no expression of HLAB on tumour cells showed worst prognosis." (PMID 30679934, 2019). "Specifically, MCC tumor significantly downregulated HLA-B, but not HLA-A at acquired resistance." (PMID 30250229, 2018). "A selective lower HLA-A expression was more frequently observed than HLA-B/C, with 11% (n = 9) of the tumours that did not or weakly expressed HLA-A and 70% (n = 57) displayed a heterogeneous expression versus 4% (n = 3) and 30% (n = 24), respectively, for HLA-B/C." (PMID 27853827, 2017). "Downregulation of HLA-B/C was observed in 82.7%; in 46%, tumours expression was totally absent." (PMID 24987709, 2014). "Downregulation of MHC genes that are involved in antigen presentation, including HLA-B/-C/-F/-G, and genes responsible for antigen processing, CTSB and HSPA2, may facilitating tumor cell evasion of immunosurveillance and, hence, increase tumor cell survival." (PMID 23024765, 2012). "In CTCL, our findings show that all three classical MHC-I proteins (HLA-A, HLA-B, and HLA-C), but not the non-classical MHC-I (HLA-E), exhibit high expression levels on tumor T cells from MF skin lesions." (PMID 38272918, 2024). "Presence of somatic variants in genes related to antigen presentation, including HLA-A, HLA-B, HLA-C, B2M (β-2-microglobulin), TAP2, and PSMB8 (LMP-7), did not predict tumor classification." (PMID 30824826, 2019). "We did not observe a difference in tumor MHC class I expression according to DCB (HLA-A: n = 26, Mann-Whitney p = 0.26, HLA-B: n = 26, Mann-Whitney p = 0.36, HLA-C: n = 26, Mann-Whitney p = 0.24)." (PMID 28552987, 2017). "Their cytotoxicity against OSC20 tumour cells was also inhibited by anti-CD8, anti-HLA class I, or anti-HLA-B, C mAb, but not by any other mAbs tested." (PMID 12966429, 2003). "In contrast, the absence of HLA-B homozygosity in HGG might reflect some selection pressure to ensure the occurrence of HLA-KIR interactions, possibly contributing to immune escape and tumor development." (PMID 38318504, 2023). "They analyzed GSC derived from primary tumor samples by mass cytometry, and the GSC expressed normal levels of NK cell activation receptor ligands (ULBP2, ULBP3, VIM) and upregulated levels of NK cell inhibitory receptor ligands (HLA-A, HLA-B, HLA-C, HLA-E, HLA-G, PCNA) compared with non-GSC." (PMID 34638384, 2021).
infection (145 papers, 2006 to 2026). The state of being infected such as from the introduction of a foreign agent such as serum, vaccine, antigenic substance or organism. "Conversely, HLA-B*15 encodes for a T but correlates with asymptomatic infection, highlighting that comprehensive future studies are required to fully delineate these associations and dissect their impact on NK cells or pre-existing T cell responses." (PMID 39487235, 2025). "The HLA-B*15 allele group (adjusted p value < 0.001) was associated with a protective factor against symptomatic infection." (PMID 40451247, 2025). "Immunoreactive epitopes in the naïve were predominantly associated with HLA‐A, which shifted to primary HLA‐B following natural infection." (PMID 40342296, 2025). "Subsequent natural infection induced novel epitopes that were dispersed across the antigen and primarily associated with HLA‐B, specifically the B7 supertype." (PMID 40342296, 2025). "We show a possible association between HLA-B*38 and HLA-C*03 alleles and protection against infection, which should be confirmed with larger cohorts to obtain greater statistical power." (PMID 39125781, 2024). "Studies have shown an association of the HLA-B*15 allele with protection from infection, while others associate it with susceptibility to infection." (PMID 39125781, 2024). "This supports that HLA-B*38 and HLA-C*03 alleles play a protective role in L. infantum infection, both in terms of protection against infection and in the development of asymptomatic disease." (PMID 39125781, 2024). "Using the UK Biobank cohort, we found a significant association between HLA-B*15:01 and asymptomatic infection." (PMID 39491366, 2024). "Nevertheless, our study showed that post-treatment control, as reported for PLWH13,16, was not related to the presence of protective MHC traits associated with natural control of infection (e.g., HLA-B*27 or B*57 alleles in PLWH or MHC-M6 haplotype in CyMs)." (PMID 38212337, 2024). "Overall, we showed that individuals carrying the HLA-B*15 allele exhibit a more favorable response to vaccines but are more susceptible to breakthrough infections caused by Omicron variants such as BA.5.2 and XBB.1.16." (PMID 39257586, 2024). "We therefore concluded that HLA-B*15 populations have a better response to SARS-CoV-2 vaccines but are more susceptible to Omicron breakthrough infection." (PMID 39257586, 2024). "For example, HLA-B*51:01 allele was protective against HIV-1 subtype B during early infection, while being associated with disease progression during HIV-1 subtype C infection." (PMID 37484179, 2023). "For example, in EUR ancestral group, HLA-B*27:05 were associated with an overall decreased risk of infection, HLA-A*11:01 were associated with less severity, while HLA-C*12:03, -B*35, -B*38:01 were associated with an increased risk of SARS-CoV-2 severity." (PMID 36649279, 2023). "The HLA-A*30, HLA-B*49, and HLA-B*57 allele groups are predisposing factors for infection by delta (B.1.617.2) viral strains." (PMID 36360904, 2022). "We show that among participants reporting a positive test result for SARS-CoV-2, HLA-B*15:01 is significantly associated with asymptomatic infection." (PMID 34031661, 2022). "In summary, we have demonstrated a strong and significant association of a common HLA class I allele, HLA-B*15:01, with asymptomatic infection with SARS-CoV-2." (PMID 34031661, 2022). "HLA-A*30, HLA-B*49, and HLA-B*57 allele groups were predisposing factors for infection by delta (B.1.617.2) strains." (PMID 36360904, 2022). "Testing only the allele of interest, we found that HLA-B*15:01 is strongly associated with asymptomatic infection in this cohort when adjusting for sex and age (p=0.02; OR=3.56, 95% CI=1.15–10.94)." (PMID 34031661, 2022). "Among all, any possible molecular mimicry-associated novel risk appeared to be prominent in HLA-A*24:02 and HLA-B*27:05 serotypes upon infection with Omicron 21L." (PMID 36412834, 2022).
infection (continued). "We tested for association of five HLA loci (HLA-A, -B, -C, -DRB1, -DQB1) with disease course and identified a strong association of HLA-B*15:01 with asymptomatic infection, and reproduced this association in two independent cohorts." (PMID 34031661, 2022). "In fact, the expression of specific HLA-B and -C alleles have been associated with higher resistance to infection by the human immunodeficiency virus type 1 (HIV-1) and with the spontaneous clearance of hepatitis C virus (HCV)." (PMID 35960731, 2022). "They identified HLA-B*46:01 as the least presenting allele and HLA-B*15:03 as the most presenting one, possible risk and protective factors of infection, respectively." (PMID 34912378, 2021). "In the 2003 SARS outbreak, caused by the SARS coronavirus (SARS-CoV) related to SARS-CoV-2, the HLA-B*46:01 was reported to be associated with infection severity in East Asian patients." (PMID 33298875, 2020). "To confirm varying TAP-dependencies of HLA-B cell surface expression, we examined TAP1-mediated cell surface induction of HLA-B molecules following further infection of selected SK19-HLA-B cell lines with a TAP1-encoding retrovirus." (PMID 29995954, 2018). "Later in infection, a compensatory mutation outside of the epitope occurs and there is a second mutation at the HLA-B*27 binding anchor of the epitope." (PMID 28769934, 2017). "We here studied the role of HLA and viral replicative capacity in a family including three HIV-infected individuals, all expressing HLA-B*81:01, an HLA allele that is highly protective in adult infection." (PMID 27608713, 2016). "The donor, ‘GM’, the grand-daughter, ‘GD’, and the HIV-infected daughter, ‘D2’, all expressed HLA-B*81:01, which is normally associated with protection against disease progression in adult infection." (PMID 27608713, 2016). "For example, Gag P146S is a common variant in CRF01_AE Clade infection (occurring in approximately 9.5% of sequences), but this site is also subject to selection pressure from both HLA-B*13:02 and HLA-B*57:01-mediated T cell responses." (PMID 26123575, 2015). "The present work focuses on a cohort of six untreated HIV-1 infected subjects, all carrying the HLA-B*5701 allele, followed longitudinally from early infection up to seven years." (PMID 25187947, 2014). "The definitive example of viral immune escape occurs in individuals expressing HLA-B*2705, in which a series of concurrent mutations takes place during the course of infection, in the KK10 epitope." (PMID 23630526, 2013). "In contrast, polymorphisms at position 97 of HLA-B alleles were more broadly associated with HIV-1 viral control during primary infection." (PMID 24245727, 2013). "The HLA-B*3501 haplotype is associated with severe HPS caused by SNV infection implying involvement of CD8+ CTLs, and the number of SNV-specific CD8+ T cells correlates with disease severity." (PMID 18716663, 2008). "Here we investigate the relationship between the genotypes of transmitted viruses and prognostic markers of disease progression and show that infection with HLA-B*57/B*5801 escape mutants is associated with lower viral load and higher CD4+ counts." (PMID 18369479, 2008). "Furthermore, T‐cell epitopes in naïve individuals were primarily recognised in association with HLA‐A, while natural infection shifted epitope associations towards HLA‐B, particularly the B7 supertype." (PMID 40342296, 2025). "Similarly, research from Russia identified HLA-B*49 as a predisposing factor for infection with the Delta variant (B.1.617.2)." (PMID 40508150, 2025). "Our study reveals that despite HLA-B*15:01 being associated with asymptomatic infection in European ancestry cohorts, 22.37% of HLA-B*15:01-positive individuals developed critical/severe disease and were hospitalized across four independent cohorts of Asian ancestry, with 4,930 participants." (PMID 40892914, 2025).
infection (continued). "HLA-A*24 was associated with infection, HLA-A*34 was increased in the control group against symptomatic disease, HLA-B*07, B*15, B*38, B*, C*03, and DR*11 were increased in the cohabitants group against controls, and HLA-B*44 was increased in the control group against cohabitants group." (PMID 39125781, 2024). "Specifically, we analyzed the association of HLA-B*38 and HLA-C*03 alleles with infection." (PMID 39125781, 2024). "HLA-B plays a role in theimmune system and may influence the susceptibility to infection or the effect ofautoimmune processes on the lung." (PMID 38097206, 2024). "Thus, our final model was adjusted only for age and sex, again showing a significant association of HLA-B*15:01 with asymptomatic infection after adjustment for these variables (OR = 2.40, 95% CI = 1.54–3.64, P = 5.67 × 10−5, Padj = 0.003)." (PMID 37468623, 2023). "Finally, a meta-analysis across all three datasets (Citizen Science, UK, CHIRP/LIINC) confirmed the strong and consistent association of HLA-B*15:01 with asymptomatic infection (P < 10−4, OR = 2.55, 95% CI = 1.73–3.77)." (PMID 37468623, 2023). "Of the HLA types, HLA-B*27:05 was most associated with susceptibility to infection (P = 0.011)." (PMID 35254093, 2022). "To understand whether additional HLA alleles might interact with HLA-B*15:01 in asymptomatic infection, we tested all pairwise two-locus haplotypes containing HLA-B." (PMID 34031661, 2022). "HIC with HLA‐B*27 and/or B*57 alleles have a tighter control of infection and as a consequence they may more efficiently eliminate infected cells." (PMID 30629340, 2019). "Indeed, we previously showed that the effect of protective HLA-I alleles, such as HLA-B*57, was abrogated by infection with a virus pre-adapted to these alleles." (PMID 31398241, 2019). "Alternatively, the association between infection outcomes and HLA alleles may reflect exceptional efficacy of HLA-B*57 to present epitopes to T cells, as has been reported for HLA-B*57 restricted epitopes on HIV gag and other HIV proteins." (PMID 26241854, 2015). "The top SNP, rs4418214 (p = 3.6×10−11, odds ratio (OR) for the C allele = 1.52) has previously been associated with control of HIV-1 viral load, with the C allele tagging the classical HLA-B alleles 57:01 and 27:05, both known to associate with lower viral load and longer survival after infection." (PMID 23935489, 2013). "In addition, we found that individuals with the HLA-B*07 and HLA-DR*13 alleles appeared to be resistant to secondary infection by DENV-3." (PMID 23818909, 2013). "To identify sequence variation within Gag associated with disease progression, we compared sequences from viral variants obtained late in infection from 5 HLA-B*57/58:01 progressors (43 sequences) and 5 HLA-B*57/58:01 LTNPs (45 sequences) with SH, using a cut-off value of 0.90." (PMID 24339913, 2013). "Thus, HLA-B*46:01 may be a susceptibility marker for SARS-CoV-2 infection, whereas the HLA-B*15:03 allele protects against this infection." (PMID 35062298, 2022). "In addition, distinct HLA-B alleles, HLA-B27, -B57-58, were associated with infection control." (PMID 36140273, 2022). "We show that individual HLA, haplotype, and full-genotype variability likely influence the capacity to respond to SARS-CoV-2 infection, and we note certain alleles in particular (e.g., HLA-B*46:01) that could be associated with more-severe infection, as previously shown with SARS-CoV." (PMID 32303592, 2020). "Taken together, this study established that the most immunoreactive epitopes varied following vaccination and subsequent natural infection, shifting from HLA‐A in the naïve to HLA‐B in the naturally infected." (PMID 40342296, 2025). "In the Hong Kong cohort, HLA-B*15:01 was relatively enriched among individuals reporting asymptomatic infection (frequency = 0.07) compared to those with symptoms (carrier frequency = 0.06), yielding an odds ratio (OR) of 1.30." (PMID 40892914, 2025).